STAT3 (signal transducer and activator of transcription 3)
Diseases named in the same sentence as STAT3 in open-access papers (continued):
Sharing a sentence is not in itself a finding about the gene and the disease.
lymphoma (continued). "SYK is capable of associating with and phosphorylating STAT3 in human B-lineage leukemia/lymphoma cells challenged with oxidative stress." (PMID 23021489, 2012). "In ALK+ ALCL, the activation of STAT3 has been strongly implicated in the pathogenesis of this lymphoma." (PMID 22852078, 2012). "Furthermore, in mantle cell lymphoma, SB-225002 overcame drug resistance by inhibiting the activation of Akt, STAT3, and p38 signaling pathways and reprogramming lymphoma-associated macrophages." (PMID 41585903, 2025). "Specifically, the STAT3 p.S614R mutation has been linked to high PD-L1 expression in lymphomas." (PMID 40243506, 2025). "In human T lymphoma cells or mouse cells, loss of STAT3 leads to prolonged activation of STAT1." (PMID 30355451, 2018). "In addition, we investigated Stat3 mutations in lymphoma cells to clarify the role of the constitutive expression of Stat3 and of its phosphorylated forms." (PMID 28415725, 2017). "Recent genetic analyses have revealed gain-of-function STAT3 mutations in lymphoid cancers leading to hyperactivation of STAT3, which may represent a potential therapeutic target." (PMID 29228628, 2017). "PD-L1 expression on some tumors may result from oncogenic pathways such as PI3 kinase signalling in gliobastomas in association with PTEN deletion, ALK and STAT3 signalling in lymphomas or mutant EGFR activity in lung tumors." (PMID 25844720, 2015). "A meta-analysis using the Oncomine database revealed a marked enrichment of the most discriminating SYK-dependent anti-apoptotic genes and confirmed STAT3 targets in 18 diagnostic classes of human leukemias and lymphomas, of which 5 were represented in multiple studies." (PMID 24851191, 2014). "In our study, initially several important single nucleotide polymorphisms (SNPs) in STAT3 (including rs2293152, rs6503695, and rs12949918), which have been associated with gene expression and lymphoma risk, were analyzed in 166 peripheral blood specimens from DLBCL patients treated with rituximab." (PMID 24624997, 2014). "However, further experimentation is needed to explore the precise mechanism by which STAT3 polymorphisms affect the lymphoma responses to R-CHOP chemotherapy." (PMID 24624997, 2014). "Because HIES patients are predisposed to lymphoma, STAT3 mutations may occur with other types of lymphoma in HIES patients." (PMID 24662938, 2014). "Thus, loss of SHP-1 and the constitutive activation of STAT3 form a vicious cycle in these lymphoma cells." (PMID 24995504, 2014). "In addition, ALK expression in this disease is linked to STAT3 phosphorylation and, hence, STAT3 may represent one of the molecular targets for this lymphoma." (PMID 40869163, 2025). "Notably, we observed a striking STAT3 activation in OPN-deficient lymphomas, suggesting that OPN-/-Faslpr/lpr tumors could rely on this pathway to survive." (PMID 36503430, 2022). "In this study, we investigated the effect of chelidonine, an alkaloid component of Chelidonium majus L., on STAT3/Bcl-2 signaling in human T leukemia/lymphoma cells, reported to have numerous effects in common with microtubule-targeting agents (MTAs)." (PMID 41683628, 2026). "By targeted delivery to M2 macrophages, chidamide sufficiently inhibited HDACs, enhanced STAT3 acetylation, reprogrammed M2 proportion into M1 phenotype, and ultimately suppressed lymphoma growth in vivo." (PMID 41915859, 2026). "In lymphoma, nuclear factor kappa B (NFκB) signaling was activated in MNCs, while signal transducer and activator of transcription 3 (STAT3) activation was increased in DLBCL with thrombosis." (PMID 42041535, 2026). "Preferentially expanded HIV+ clonal populations with STAT3 integration sites showed increased expression and activation of STAT3, leading to a STAT3-associated increase in anti-apoptotic and cytotoxic factors, expression signatures similar to ALCL lymphomas." (PMID 40627772, 2025).
lymphoma (continued). "Then the number of macrophages (using BrdU as a macrophage marker), lymphoma cells' nuclei size and proliferation, and Stat3 and C5a levels were studied." (PMID 41030738, 2025). "Within all the lymphomas, the protein product of the LTR-promoted allele of STAT3 was in its active phosphorylated state." (PMID 40627772, 2025). "GA further demonstrates synergy with adoptive cell therapy: in lymphoma models, it modulates the STAT3 pathway to enhance anti-CD19 CAR-T cell proliferation, reduce therapy-related toxicity, and prolong CAR-T persistence in tumors." (PMID 41181090, 2025). "Treatment with the STAT3 degrader effectively induces STAT3 protein degradation both in vitro and in vivo, leading to robust suppression of its transcriptional network in leukemia and lymphoma cells and resulting in sustained tumor regression." (PMID 40227962, 2025). "Currently, several strategies involving the combination of BCL6 inhibitors with several agents, including PRMT5 inhibitors, EZH2 inhibitors, STAT3 inhibitors and chemotherapy drug doxorubicin, have been explored for the treatment of lymphomas." (PMID 39815148, 2025). "Constitutive activation of STAT3 has been observed in both solid tumors and hematological malignancies, such as leukemia and lymphoma, and serves as a prognostic marker for disease progression." (PMID 40166646, 2025). "Quantification of data confirmed elevated levels of tyrosine phosphorylation of both STAT1 and STAT3 and reduced levels of both NF-κB and IκBα in lymphoma cells from mice expressing STAT1-∆N." (PMID 40287766, 2025). "In contrast to most types of human B cell lymphomas (including EBV-infected lymphomas that express the EBV LMP1 oncoprotein), reduced NF-κB and STAT3 activity is a hallmark of human Burkitt lymphomas." (PMID 38620028, 2024). "Silencing Stat-3 expression or suppressing Stat-3 activity has been shown to decrease PD-L1 expression in NK/T lymphoma cell lines." (PMID 39013845, 2024). "The diagnoses of the patients included primary immunodeficiency diseases (DOCK8: n=4, STAT3: n=1, GATA2 mutations: n=11), lymphoma (n=3), leukemia (n=5), and sickle cell disease (n=5)." (PMID 38756303, 2024). "Targeting JAK/STAT3 signaling can inhibit tumor growth and enhance antitumor immune responses, making STAT3 a promising therapeutic target in lymphoma." (PMID 38817669, 2024). "Additional studies are necessary to explore, dissect, and therapeutically perturb the IL-6/JAK/STAT3 pathway in EBV+ lymphomas." (PMID 38915538, 2024). "RNA-seq analysis also showed that the Myc-expressing lymphomas, like human BLs, have decreased expression of the NF-κB2 and STAT3 transcripts, as well as decreased Src kinase transcripts." (PMID 38620028, 2024). "The results demonstrated that lymphoma cells can activate the Notch-1 downstream STAT3/STAT6 signaling pathway." (PMID 38261741, 2024). "The administration of the CD19-SMCC-protamine-STAT3 siRNA conjugate in vivo also led to the inhibition of A20 lymphoma progression." (PMID 37686472, 2023). "STAT3 is overexpressed in lymphoma cells and the expression level correlates with a worse prognosis." (PMID 37686472, 2023). "At the molecular level, we found that NFE2L2 and STAT3 converged in the regulation of several pro-survival molecules and in the activation of processes essential for the adaption of lymphoma cells to stress." (PMID 37511362, 2023). "JAK-1 is known to be the main activator for STAT-3 activity, and excessive STAT-3 activation is common in lymphoma." (PMID 37175040, 2023). "The binding of the CD19-SMCC-protamine-STAT3 siRNA conjugate in vitro was tested using splenic lymphocytes and the lymphoma A20 cell line originated from B cells." (PMID 37686472, 2023). "The SU-DHL-2 and OCI-Ly3 lymphoma cells incubated with CSP-STAT3 siRNA conjugates also exhibited significantly reduced STAT3 expression." (PMID 37686472, 2023). "PROTAC SD-36 is designed to promote STAT3 degradation and suppress cell proliferation in lymphoma and leukemia." (PMID 37288663, 2023).
lymphoma (continued). "MS4077 and MS4078 potently reduced the levels of oncogenic active ALK fusion proteins and inhibited ALK and STAT3 phosphorylation in SU-DHL-1 lymphoma and NCI-H2228 lung cancer cells." (PMID 36986673, 2023). "Recently, Wang’s group reported a potent and effective STAT3 degrader SD-36, which selectively induced rapid STAT3 degradation at low nanomolar concentrations in leukemia and lymphoma cells, and achieved nanomolar cytostatic activity." (PMID 36034876, 2022). "We previously reported that lymphoma cell-derived IL-27 significantly enhanced PD-L1 expression on TAMs via the STAT3 pathway." (PMID 35835809, 2022). "Of note, recent studies indicated that STAT3 expression critically regulates ferroptosis in various diseases, including acute lung injury and lymphoma." (PMID 36506580, 2022). "Since STAT3 is a client of HSP90 and is involved in the regulation of immune checkpoints, we sought to analyze STAT3 expression in activated T cells of lymphoma patients." (PMID 36359267, 2022). "Blood Cancers: Along with CuI-mediated apoptotic response in CD4+T cells from patients with Sezary syndrome, an aggressive type of lymphoma, CuI (30 μM) also induced a reduction in p-STAT3 (as well as total STAT3 levels)." (PMID 36355554, 2022). "STAT3 constitutively active in many human cancer cells including MM, leukemia, lymphoma, and solid tumors." (PMID 35503759, 2022). "Functionally in certain leukemia and lymphoma cell lines SD-36 inhibited STAT3 dimerization, DNA binding and target gene activity." (PMID 35844493, 2022). "It has been reported that escape from drug toxicity via STAT3 contributed to GCs resistance in lymphomas." (PMID 35252347, 2022). "A representative inhibitor of STAT3 is stattic (PubChem ID: 2779853), which interrupts the tumor cell growth by inhibiting lymphoma activity." (PMID 35216171, 2022). "Next-generation sequencing of ENKTL and aggressive NK-cell leukemia (ANKL) has shown recurrent mutations in the JAK/STAT pathway, particularly in STAT3 and STAT5B in both lymphoma entities." (PMID 35330161, 2022). "In a series of 84 ENKTL lymphomas sequenced for JAK3 and STAT3, JAK3 mutations were discovered in 7% of cases, while STAT3 mutations were less common, with only one case found to be mutated." (PMID 35628826, 2022). "AZD9150, a next-generation antisense oligonucleotide inhibitor of STAT3, also demonstrated potent anti-tumor effects of lymphoma cell lines and in preclinical lymphoma models." (PMID 36304465, 2022). "NPM-ALK, CLTC-ALK, and SQSTM1-ALK translocations lead to ALK and STAT3 phosphorylation with downstream oncogenic activation of the transcription factor STAT3, which enhances lymphoma cell proliferation and growth." (PMID 34283060, 2021). "Inhibitors that are able to attenuate JAK1/STAT3 signalling have been shown to suppress cell proliferation of lymphoma and oesophageal cancer." (PMID 33523587, 2021). "In advanced stages of a lymphoma, STAT3 and STAT5 are completely dependent on the constitutively activated JAK1 and JAK3." (PMID 34948183, 2021). "Our finding is also consistent with a previous report that PD-L1/2 overexpression was dependent on activation of Stat3 in TAMs in human lymphoma." (PMID 33749663, 2021). "In this study, SD-36 efficiently degrades STAT3 in vitro in various leukemia and lymphoma cell lines." (PMID 34440253, 2021). "By analyzing the HDAC3 role on the acetylation of STAT3 K685 in malignant lymphoma, the authors showed that HDAC negatively regulated this PTM, i.e., HDAC overexpression decreased AcSTAT3 K685 levels, while HDAC knockdown upregulated acetylation of STAT3." (PMID 34440160, 2021). "Previous studies showed that STAT inhibitors can inhibit STAT3 protein expression in lymphoma and have early clinical activity." (PMID 34745261, 2021). "The constitutive activation of the NF-κB and JAK/STAT3 signaling is perhaps the main feature of the lymphomas belonging to these subtypes." (PMID 36046113, 2021).
lymphoma (continued). "AZD9150 (ASO targeting STAT3) was demonstrated to be effective for treating patients with lymphoma in a phase 1b trial." (PMID 34185427, 2021). "Activated STAT3 confers a T-regulatory phenotype to NPM-ALK(+) lymphoma cells and potentially contributes to their ability to evade the host’s immune response." (PMID 33466277, 2021). "Recently, Zhang et al58 demonstrated that IKBKE played an important role in maintaining the activity of STAT3 in lymphoma cell lines, thereby accelerating lymphoma growth and malignant progression." (PMID 31733040, 2020). "Oncogenic activation of STAT3 drives strong PD-L1 expression in lymphoma, by increasing STAT3 transcriptional activity and ensuring robust binding to the PD-L1 promoter." (PMID 32992658, 2020). "The activation of JAK/STAT3 pathway promotes the occurrence and development of various diseases, including inflammatory diseases, lymphomas, leukemias, and solid tumors (Bhat, Goel, Shukla, & Hanif, 2016)." (PMID 32955171, 2020). "In silico screening studies followed by STAT3-dependent luciferase reporter gene assays led to the identification of STX-0119, another STAT3 inhibitor impacting the growth of lymphoma cell lines." (PMID 31963765, 2020). "In the ENKTCL arising in East Asia, genetic analyses have shown that activating mutations of the JAK-STAT pathway, such as in JAK3 (5–35%), STAT3 (6–27%) and STAT5B (2–6%) genes are characteristic of this lymphoma." (PMID 32759793, 2020). "RNA interference (RNAi) or antisense oligonucleotides (ASO) were also employed to target STAT3/5 mRNA in leukemia or lymphoma cells." (PMID 31963765, 2020). "SD-36 was shown to induce STAT3 degradation, cell growth arrest, and apoptosis in lymphoma and leukemia cells lines as well as tumor regression in multiple xenograft mouse models of leukemias and lymphomas." (PMID 31963765, 2020). "Inhibition of STAT3 expression/activity in ABC-DLBCL cells abrogates lymphoma cell growth and triggers apoptosis." (PMID 31963765, 2020). "Since SYK activation is directly caused by mutated MYD88 and mediates its downstream STAT3 and AKT signaling, we next sought to clarify the importance of SYK in supporting cell growth and survival in MYD88-mutated lymphoma cells." (PMID 32005797, 2020). "Inhibitory effects of AZD9150 on STAT3 expression and cell growth were also demonstrated in preclinical models of lymphomas." (PMID 31963765, 2020). "Previous studies have shown that PD-L1 is expressed in lymphoma, and is transcriptionally regulated by Stat3." (PMID 32317968, 2020). "Oral administration of STX-0119 was shown to reduce STAT3 target gene expression and to induce apoptosis in a xenograft model of lymphoma." (PMID 31963765, 2020). "As a possible explanation for these findings, combined treatment abolished the phosphorylation of IGF-IR and NPM-ALK as well as the phosphorylation of their common downstream target STAT3; a major survival-promoting transcription factor in this lymphoma." (PMID 31340850, 2019). "In this review, we focus on the oncogenic role of STAT3 in human lymphoma and highlight potential therapeutic intervention by targeting JAK/STAT3 signaling." (PMID 31861597, 2019). "Whereas phosphorylated IGF-IR, NPM-ALK, and STAT3 appeared to be almost completely abrogated by PPP combined with ASP3026 in the lymphoma cells, PPP or ASP3026 alone induced significantly lesser effects on these survival-promoting proteins." (PMID 31340850, 2019). "The cell lines were responsive to treatment with a JAK inhibitor, which highlights both the importance of dysregulated STAT3 in this aggressive lymphoma and suggests a therapeutic benefit to targeting the JAK/STAT pathway." (PMID 31684088, 2019). "In adult T-cell lymphoma, IL-27B production by Lymphoma cells and IL-27p28 production by macrophages lead to STAT3 activation and PD-L1/L2 expression in macrophages." (PMID 31480382, 2019).
lymphoma (continued). "Although STAT3 expression is properly controlled in normal immune responses, constitutive activation of STAT3 is common in human lymphoma." (PMID 31861597, 2019). "Lastly, STAT3 decoy oligonucleotides demonstrated activity in lymphoma in preclinical studies, but suffered from poor bioavailability and short half-lives in vivo due to rapid nuclease degradation, which limits their clinical application." (PMID 31684088, 2019). "Previously, a constitutive oncogenic pathway has been reported to drive PD‐L1 expression through signal transducer and activator of transcription 3 (STAT3) signalling in lymphoma cells." (PMID 29726585, 2018). "We now have strong evidence that STAT3/NF-κB activity driven by either a complex microenvironment in lymphomas or intrinsic genetic lesions is important in the metabolic reprogramming of cells different from OxPhos DLBCL." (PMID 29666362, 2018). "Without the need for pharmacological formulation, the unformulated CpG(B)-STAT3dODN, injected locally or systemically, was effective in blocking STAT3 in lymphoma cells." (PMID 29433938, 2018). "Expression of the several STAT3-controlled mediators of lymphoma cell proliferation and survival, including Bcl2l1, Bcl6, Casp3, Ccnd3, and Myc, was reduced." (PMID 29433938, 2018). "Our results suggested that modified CpG(B)-STAT3dODN can effectively penetrate into immune and lymphoma cells, thereby enabling STAT3 targeting." (PMID 29433938, 2018). "We have previously reported the efficient uptake and STAT3 knockdown capacity of AZD9150 in patient-derived tumor explant models of lymphoma." (PMID 30446007, 2018). "In order to investigate the molecular pathways involved in the regulation of proliferation and apoptosis driven by CDK5, we measured the expression of STAT3-specific targets in lymphoma cells expressing CDK5-specific shRNAs." (PMID 28640256, 2017). "To determine what the extent of THZ1 anti-lymphoma activity is due to STAT3 inhibition, we treated OCI-Ly12 and OCI-Ly13.2 cells with selective STAT3 inhibitor compounds." (PMID 28134252, 2017). "It was reported that STAT3 phosphorylation induced by LFA-1 (αLβ2) cross-linking promoted the migration of T-lymphoma cell line via binding with microtubule-destabilizing protein stathmin." (PMID 26848618, 2016). "Mutations in the DNA-binding or transactivation domain of STAT3 in hyper-IgE syndrome patients are known to negatively impact immune cell function and exacerbate infectious disease and EBV lymphomas (60, –, 64)." (PMID 27486189, 2016). "Results also highlight the potential utility of a signature involving Bcl-2 overexpression, Rac1 activation and STAT3 phosphorylation for stratifying clinical lymphomas based on disease severity and chemoresistance." (PMID 26430964, 2015). "We performed expression analyses for STAT3pTyr705 and STAT3pSer727, total STAT3, Bcl-2pSer70), total Bcl-2 and Rac1, in lysates obtained from cells isolated from biopsies from 41 patients diagnosed with lymphomas." (PMID 26430964, 2015). "The distinctive mBL signature consisted of 58 genes, including several target genes of the NF-κB pathway (i.e., BCL2A1, FLIP, CD44, NFKBIA, BCL3, and STAT3) that are known to distinguish activated B-cell-like or germinal center B-cell-like lymphomas." (PMID 26416427, 2015). "STAT3 is constitutively activated also in Primary Effusion Lymphoma (PEL) cells and its inhibition leads to apoptotic cell death." (PMID 26338963, 2015). "Here we investigated the effects of STAT3 deletion in a BCR/ABL-induced lymphoma model, which is tightly controlled by natural killer (NK) cells in vivo." (PMID 24473086, 2014). "On the other hand, it has been reported in a lymphoma cell line that the Cbp-Lyn complex phosphorylates signal transducer and activator of transcription 3 (STAT3) in lipid rafts, resulting in the efficient activation of transforming signals." (PMID 24675741, 2014).